ST3GAL3 (ST3 beta-galactoside alpha-2,3-sialyltransferase 3)
Description:
Catalyzes the formation of the NeuAc-alpha-2,3-Gal-beta-1,4-GlcNAc-, NeuAc-alpha-2,3-Gal-beta-1,3-GlcNAc- and NeuAc-alpha-2,3-Gal-beta-1,3-GalNAc-sequences found in terminal carbohydrate groups of glycoproteins and glycolipids. The highest activity is toward Gal-beta-1,3-GlcNAc and the lowest toward Gal-beta-1,3-GalNAc.
Synonyms: ST3GalIII; SIAT6; DEE15; EIEE15; MRT12; ST3GALII; ST3Gal III; ST3N
Tractability: Antibody: UniProt places it where antibodies can reach, with medium confidence; UniProt predicts a signal peptide or a membrane-spanning region; its Gene Ontology location is reachable by antibodies, with medium confidence. PROTAC: ubiquitination databases record sites on it; its protein half-life has been measured; a small molecule that binds it is known.
Target class: Enzyme; Transferase
Gene: Protein-coding gene on chromosome 1 (43,705,824 to 43,931,167, forward strand). Ensembl gene ENSG00000126091.
Subcellular location: Golgi apparatus, Golgi stack membrane; Secreted
Pathways (Reactome):
Disease: Defective ST3GAL3 causes MCT12 and EIEE15; Maturation of protein 3a; Maturation of spike protein
Metabolism: Glycosphingolipid biosynthesis; Keratan sulfate biosynthesis; Lewis blood group biosynthesis
Metabolism of proteins: Sialic acid metabolism; Termination of O-glycan biosynthesis
Signal Transduction: Pre-NOTCH Processing in Golgi
Gene Ontology:
Molecular function: protein binding; beta-D-galactosyl-(1->3)-N-acetyl-beta-D-galactosaminide alpha-2,3- sialyltransferase; beta-galactoside (CMP) alpha-2,3-sialyltransferase activity; N-acetyllactosaminide alpha-2,3-sialyltransferase activity; sialyltransferase activity
Biological process: glycoprotein biosynthetic process; glycosphingolipid biosynthetic process; keratan sulfate proteoglycan biosynthetic process; oligosaccharide biosynthetic process; protein O-linked glycosylation via N-acetyl-galactosamine; viral protein processing; ganglioside biosynthetic process
Cellular component: Golgi membrane; extracellular region; Golgi cisterna membrane
Genetic constraint (gnomAD): Loss-of-function variants: 21 observed, 52.82 expected, observed/expected ratio (o/e) 0.4, 90% interval 0.28 to 0.57. The upper end of that interval is the gene's LOEUF score, 0.57, which puts it in group 2 of 6, group 1 being the genes least tolerant of losing a copy. Missense variants: 353 observed, 515.88 expected, observed/expected ratio (o/e) 0.68, 90% interval 0.63 to 0.75. Synonymous variants: 183 observed, 199.65 expected, observed/expected ratio (o/e) 0.92, 90% interval 0.81 to 1.04.
Gene-disease validity (ClinGen):
ClinGen rates the evidence that ST3GAL3 causes each of these diseases.
complex neurodevelopmental disorder (autosomal recessive): Moderate. A disorder that involves more than one phenotype associated with the central nervous system, including but not limited to intellectual disability, autism, and seizures (epilepsy).
Homologues: Orthologues: chimpanzee ST3GAL3 (99% identical), macaque ST3GAL3 (99% identical), dog ST3GAL3 (99% identical), pig ST3GAL3 (98% identical), rabbit ST3GAL3 (98% identical), rat St3gal3 (97% identical), mouse St3gal3 (97% identical), guinea pig ST3GAL3 (89% identical), tropical clawed frog st3gal3 (83% identical), zebrafish st3gal3b (65% identical), zebrafish st3gal3a (62% identical). Paralogues in human: ST3GAL5 (35% identical), ST3GAL4 (32% identical), ST3GAL6 (28% identical), ST6GALNAC2 (23% identical), ST3GAL1 (22% identical), ST3GAL2 (22% identical), ST6GAL2 (21% identical), ST6GALNAC1 (21% identical), ST6GAL1 (18% identical), ST6GALNAC5 (15% identical), ST6GALNAC4 (15% identical), ST6GALNAC6 (14% identical), and 2 more.
Diseases named in the same sentence as ST3GAL3 in open-access papers:
ST3GAL3 is named in the same sentence as 61 diseases in open-access papers, as found by Europe PMC text mining. Sharing a sentence is not in itself a finding about the gene and the disease. The quoted sentences say what the papers report.
pancreatic cancer (11 papers, 2010 to 2022). "Among them, ST3GAL1 overexpression promotes epithelial-mesenchymal transition, migration, and invasion in ovarian cancer, and ST3GAL3 downregulation inhibits pancreatic cancer cell migration and invasion." (PMID 36605200, 2022). "The migration, invasion, and E-selectin-dependent adhesion of pancreatic cancer cells were consistently reduced when ST3GAL3 or ST3GAL4 expression was downregulated." (PMID 36547200, 2022). "Consistently, downregulation of either ST3GAL3 or ST3GAL4 decreased pancreatic cancer cell migration, invasion and E-selectin-dependent adhesion." (PMID 33921986, 2021). "Overall, we have shown that STs, and in particular ST3GAL4 and ST3GAL3 that lead to the sLex/a biosynthesis can be considered as potential therapeutic targets against pancreatic cancer." (PMID 32872308, 2020). "To further investigate the functional importance of ST3GAL4 and ST3GAL3 in the binding of pancreatic tumor cells to E-selectin, we also analyzed this adhesive interaction under dynamic flow conditions using a microfluidic system." (PMID 32872308, 2020). "Overexpression of ST3GAL3 in pancreatic cell lines induced increased expression of sLeX together with decreased α2,6 sialylation on α2β1 integrin and E-cadherin, which further regulate adhesion and invasion in pancreatic cancer." (PMID 32582529, 2020). "The overexpressed ST3GAL3 and ST3GAL4 in pancreatic cancer increase the biosynthesis of the sialic acid-Lewis (sLe) antigen, thus promoting tumor metastasis." (PMID 36092699, 2022). "It has been demonstrated that ST3GAL3 and ST3GAL4 increase the adhesion, motility, and migration of pancreatic cancer cells in vitro and the potential for metastasis in vivo." (PMID 36547200, 2022). "ST3GAL3 and ST3GAL4 have been shown to promote pancreatic cancer cell adhesion, motility and migration in vitro and to enhance metastatic potential in vivo." (PMID 33921986, 2021). "In this work, we have addressed the impact of the downregulation of the α2,3-sialyltransferases ST3GAL3 and ST3GAL4 (which regulate sLex and sLea biosynthesis) on migration, invasion and E-selectin-dependent adhesion of pancreatic cancer cells." (PMID 32872308, 2020). "ST3GAL3 and ST3GAL4 were knocked down via shRNA in two pancreatic cancer cell lines, BxPC-3 and Capan-1, whose scramble (SC) control cells display high to moderate levels of sLex." (PMID 32872308, 2020). "Amongst them, PLD1, EGFR, ST3GAL3 and ARF6 mediate the progression of pancreatic cancer." (PMID 33493138, 2021).
Intellectual disability (9 papers, 2014 to 2025). "Notably, aph1b (neurodevelopmental disorders) and st3gal3 (intellectual disability and behavioral disorders) were implicated in disrupted synaptic maturation." (PMID 41310639, 2025). "ST3GAL3 deficiency is a rare autosomal recessive disorder caused by pathogenic mutations in the ST3GAL3 gene and characterized by epilepsy, motor development delay, severe intellectual disability and behavioral disorders." (PMID 35794776, 2023). "Taken together, pathogenic variants of ST3GAL3 lead to glycosylation deficiency of gangliosides and glycoproteins, and subsequently to cognitive dysfunction, and patients with pathogenic ST3GAL3 exhibit severe intellectual disability, developmental delay, and DEE." (PMID 39858526, 2025). "Furthermore, one of the top GWAS signals for ADHD is located on chromosome 1 in ST3GAL3, a sialyltransferase gene linked with intellectual disability, which has also been linked with cognitive deficits and demyelination in genetically modified mice deficient in St3gal3." (PMID 33339955, 2021). "ST3GAL3 loss-of-function variants result in West syndrome, a DEE syndrome with developmental regression and intellectual disability, and severe nonsyndromic autosomal recessive intellectual disability (NSARID)." (PMID 39858526, 2025). "ST3GAL3‐related developmental and epileptic encephalopathy (DEE‐15) is an autosomal recessive condition characterized by intellectual disability, language and motor impairments, behavioral difficulties, stereotypies, and epilepsy." (PMID 37067065, 2023). "In addition to their association with DEE15, ST3GAL3 defects can lead to MRT12 (OMIM #611090), which is characterized by nonsyndromic severe intellectual disability without seizures or early psychomotor developmental delays." (PMID 37938134, 2023).
cognitive deficits (8 papers, 2020 to 2026). "For example, it was seen that mice deficient in sialyltransferases St3gal2 and St3gal3 (mainly involved in the assembly of gangliosides) presented motor impairments and cognitive deficits, besides increased dysmyelination, indicating the crucial role of sialylation." (PMID 33993882, 2021). "These mice were shown to have lowered MBP protein expression in the PFC, as well as cognitive deficits in male St3gal3+/− mice, and increased activity and enhanced cognitive control in female St3gal3+/− mice." (PMID 36291644, 2022). "Our results reveal that male St3gal3 HET mice display cognitive deficits, while female HET animals show increased activity, as well as increased cognitive control, compared to their wildtype littermates." (PMID 34650588, 2021).
ovarian carcinoma (8 papers, 2010 to 2025). A malignant neoplasm originating from the surface ovarian epithelium. "St3gal3 is an enzyme responsible for catalyzing the synthesis of α2,3-linked sialic acids, which play a crucial role in promoting immune evasion and tumor progression in ovarian cancer." (PMID 40330466, 2025). "They further suggest that overexpression of ST3Gal3 may serve as a diagnostic and prognostic marker and also a potential chemotherapeutic target for ovarian cancer." (PMID 36547200, 2022). "Similar studies conducted have held ST3GAL3 accountable for paclitaxel-related resistance during ovarian cancer chemotherapy." (PMID 36547200, 2022). "One such sialyltransferase is ST3GAL3, whose mRNA expression levels differed significantly amongst different ovarian cancer cell lines." (PMID 36547200, 2022). "In ovarian cancer, ST3GAL3 KD sensitized ovarian cancer cells to cisplatin and paclitaxel induced apoptosis." (PMID 32872308, 2020). "Thus, targeting St3gal3 and sialylation offers a promising strategy to enhance the effectiveness of immunotherapy in ovarian cancer." (PMID 40330466, 2025). "Their findings light on the reverse correlation between the expression levels of ST3GAL3 and the dosage of cisplatin used in various cell lines and claim that by targeting ST3GAL3, chemoresistance of cisplatin can be prevented the relapse of ovarian cancer." (PMID 36547200, 2022).
breast carcinoma (7 papers, 2010 to 2022). "ST3GAL3 expression in patients with breast cancer was strongly associated with poor prognosis and reduced overall survival." (PMID 25923697, 2015). "For instance, ST3GAL3 modulated breast cancer cell adhesion and invasion by inducing the expression of invasion-related molecules, including β1 integrin, matrix metalloproteinase (MMP)-2, MMP-9 and COX-2." (PMID 33921986, 2021).
developmental delay (5 papers, 2014 to 2025). "Herein, we report a case of a male patient with ST3GAL3 gene variants from a Chinese family, who presented with epileptic encephalopathy and psychomotor developmental delay." (PMID 37938134, 2023). "In summary, we reported a rare case of DEE with severe psychomotor developmental delays and seizures and identified two novel variants of the ST3GAL3 gene that are associated with this condition." (PMID 37938134, 2023). "Genetic deficiency of sialyltransferase ST3GAL3 (OMIM#611090) and ST3GAL5 (OMIM#609056), two enzymes that add sialic acid residues to glycoproteins and glycolipids, leads to infantile epilepsy and developmental delay." (PMID 34163424, 2021).
glioma (5 papers, 2010 to 2024). A benign or malignant brain and spinal cord tumor that arises from glial cells (astrocytes, oligodendrocytes, ependymal cells). "The expressions of ST3GAL3, 4, and 6 are known to be higher in high-grade gliomas compared to low-grade gliomas." (PMID 38067186, 2023). "Thus, transfection of glioma cells U-373 MG α2,3-sialyltransferase III (ST3GAL3), which increases the content of terminal α2,3-linked sialic acids, resulted in a phenotype of glioma cells with increased invasiveness." (PMID 39728102, 2024). "Furthermore, high-grade glioma cell lines exhibit higher expression of terminal sLeX and of the SiaTs ST3Gal3/4/6 compared to low-grade glioma cells." (PMID 34975914, 2021). "High-grade glioma cells showed overexpression of several sialyl- and fucosyltransferases involved in the biosynthesis of Lewis glycans and the high expression of SLex could be attributed to the expression of FUT7/11 and ST3GAL3." (PMID 33447350, 2020).
colon carcinoma (4 papers, 2010 to 2021). "Intriguingly, the induction of epithelial-mesenchymal transition (EMT) in colon cancer led to the upregulation of FUT3, ST3GAL3 and ST3GAL4, which are implicated in the final steps of the biosynthesis of sLex/a, suggesting a significant link between those Lewis antigens and EMT in colon carcinoma." (PMID 32872308, 2020). "Previous study indicates that NEU4 desialylates cell surface sLeA/X to LeA/X without affecting the expression of ST3GAL3, ST3GAL4, FUT3, and FUT7 in colon cancer cells." (PMID 34135905, 2021).
gastric cancer (4 papers, 2013 to 2020). A primary or metastatic malignant neoplasm involving the stomach. "Similar results on higher ST3GAL4 relative to ST3GAL3 expression have also been reported in gastric carcinoma." (PMID 32872308, 2020). "In gastric cancer, the expression levels of ST3GAL3 and FUT4 mRNA were significantly enhanced in carcinoma tissues." (PMID 25923697, 2015). "In this study we determined the capacity of ST3GAL3 and ST3GAL4 sialyltransferases to synthesize the SLex antigen in MKN45 gastric carcinoma cells and evaluated the effect of SLex overexpression in cancer cell behavior both in vitro and in vivo using the chicken chorioallantoic membrane (CAM) model." (PMID 23799130, 2013).
pancreatic adenocarcinoma (4 papers, 2010 to 2021). "In pancreatic adenocarcinoma, overexpression of ST3GAL3 correlates with tumor progression." (PMID 35071226, 2021).
epilepsy (3 papers, 2021 to 2023). A brain disorder characterized by episodes of abnormally increased neuronal discharge resulting in transient episodes of sensory or motor neurological dysfunction, or psychic dysfunction. "Herein, we report two siblings with ST3GAL3‐related DEE with novel pathogenic variants in ST3GAL3 and further add to the phenotypic spectrum of epilepsy in this condition." (PMID 37067065, 2023). "A comprehensive review of the literature on ST3GAL3‐related CDG with a focus on epilepsy is also presented." (PMID 37067065, 2023). "In summary, we demonstrate that the spectrum of epilepsy in ST3GAL3‐related DEE may include early onset infantile seizures in the form of epileptic spasms with evolution to LGS." (PMID 37067065, 2023). "Although it is difficult to draw precise conclusions regarding the most effective ASM treatment for ST3GAL3‐related DEE given the small numbers, this may depend on the seizure and epilepsy type." (PMID 37067065, 2023).
schizophrenia (3 papers, 2020 to 2022). A major psychotic disorder characterized by abnormalities in the perception or expression of reality. "A more recent GWAS also revealed a relationship between the increased expression of a ST3GAL3 transcript in the human foetal brain and a risk for ADHD and schizophrenia." (PMID 36291644, 2022). "Whereas the most significant gene observed in the CUD and schizophrenia meta-analysis was ST3GAL3 (P = 9.68 × 10−16) and in the ND and schizophrenia meta-analysis the gene ZFYVE21 (P = 1.11 × 10−14)." (PMID 36151087, 2022).
West syndrome (3 papers, 2021 to 2023). "ST3GAL3 was initially associated with nonsyndromic autosomal recessive intellectual disability, and later, ST3GAL3 gene defects were identified in a family with West syndrome." (PMID 37938134, 2023). "Although loss-of-function mutations in ST3GAL3 are implicated in non-syndromic autosomal recessive intellectual disability (NSARID) and West syndrome, the impact of ST3GAL3 haploinsufficiency on brain function and the pathophysiology of neurodevelopmental disorders (NDDs), such as ADHD, is unknown." (PMID 34650588, 2021). "Infantile epileptic spasms syndrome (IESS) and Lennox Gastaut syndrome (LGS) have been described in some cases of ST3GAL3‐related DEE." (PMID 37067065, 2023).
attention deficit-hyperactivity disorder (2 papers, 2021). A disorder characterized by a marked pattern of inattention and/or hyperactivity-impulsivity that is inconsistent with developmental level and clearly interferes with functioning in at least two settings (e.g. at home and at school). "GWAS have reported associations between SNPs encoding ST3GAL3 and the incidence of schizophrenia, attention-deficit/hyperactivity disorder (ADHD) and autistic spectrum disorders (ASD)." (PMID 34944404, 2021). "Genome wide association meta-analysis identified ST3GAL3, a gene encoding the beta-galactosidase-alpha-2,3-sialyltransferase-III, as a risk gene for attention-deficit/hyperactivity disorder (ADHD)." (PMID 34650588, 2021).
autosomal recessive intellectual disability (2 papers, 2022 to 2023). "The ST3GAL3 gene is linked to non-syndromic autosomal recessive intellectual disability as well as ADHD." (PMID 36310845, 2022).
cervical cancer (2 papers, 2010 to 2018). A primary or metastatic malignant neoplasm involving the cervix. "Moreover, it was found that high expression of ST6GAL1 was associated with more invasive properties of cervical cancer and that the reduced expression of ST3GAL1, ST3GAL3, and ST3GAL4 may also contribute to the characteristics of cervical cancer." (PMID 30375371, 2018).
oral squamous cell carcinoma (2 papers, 2021). "Furthermore, elevated ST3GAL2 and ST3GAL3 mRNA expression is associated with advanced stages of oral squamous cell carcinoma with lymph node involvement, suggesting a role of these two sialyltransferases in oral squamous cell carcinoma progression." (PMID 33921986, 2021).
pancreatic ductal adenocarcinoma (2 papers, 2015 to 2023). An infiltrating adenocarcinoma that arises from the epithelial cells of the pancreas. "A previous study showed that knockdown of ST3GAL3 led to a significant increase in cell migration and invasion in pancreatic ductal adenocarcinoma." (PMID 35637613, 2023).
benign meningioma (1 paper, 2024). A grade I, slowly growing meningioma. "In the meningioma cell lines, mRNA expression of ST6GAL1 was highly expressed in the primary benign meningiomas—SUT-MG12 and SUT-MG14—while the mRNA expression of ST3GAL1 and ST3GAL3 was observed in the malignant meningioma cell lines—HKBMM and IOMM-Lee." (PMID 38274327, 2024).
Cerebellar atrophy (1 paper, 2023). Cerebellar atrophy is defined as a cerebellum with initially normal structures, in a posterior fossa with normal size, which displays enlarged fissures (interfolial spaces) in comparison to the foliae secondary to loss of tissue. "Although most types of CDG show cerebral and/or cerebellar atrophy on neuroimaging, these findings have not been associated with ST3GAL3 pathogenic variants to date." (PMID 37067065, 2023).
colorectal cancer (1 paper, 2018). A primary or metastatic malignant neoplasm that affects the colon or rectum. "In adult cancers, such as breast and colorectal cancer, it has been demonstrated that overexpression of ST3Gal3 and FUT4 is associated with poor prognosis." (PMID 30344930, 2018).
congenital disorder of glycosylation (1 paper, 2023). Congenital disorder of glycosylation (CDG) is a fast growing group of inborn errors of metabolism characterized by defective activity of enzymes that participate in glycosylation (modification of proteins and other macromolecules by adding and processing of oligosaccharide side chains). "Only twenty‐four individuals with ST3GAL3‐related congenital disorder of glycosylation (CDG) have been described in the literature." (PMID 37067065, 2023).